CALR3 (calreticulin 3)
Description:
During spermatogenesis, may act as a lectin-independent chaperone for specific client proteins such as ADAM3. Required for sperm fertility (By similarity). CALR3 capacity for calcium-binding may be absent or much lower than that of CALR.
Synonyms: CRT2; FLJ25355; MGC26577; CT93; CMH19
Tractability: Antibody: UniProt predicts a signal peptide or a membrane-spanning region.
Gene: Protein-coding gene on chromosome 19 (16,479,061 to 16,496,167, reverse strand). Ensembl gene ENSG00000269058.
Subcellular location: Endoplasmic reticulum lumen
Gene Ontology:
Molecular function: calcium ion binding; protein folding chaperone
Biological process: ERAD pathway; protein folding
Cellular component: endoplasmic reticulum lumen; nuclear envelope; endoplasmic reticulum
Genetic constraint (gnomAD): Loss-of-function variants: 35 observed, 45.15 expected, observed/expected ratio (o/e) 0.78, 90% interval 0.59 to 1.03. The upper end of that interval is the gene's LOEUF score, 1.03, which puts it in group 4 of 6, group 1 being the genes least tolerant of losing a copy. Missense variants: 405 observed, 446.87 expected, observed/expected ratio (o/e) 0.91, 90% interval 0.83 to 0.98. Synonymous variants: 171 observed, 165.18 expected, observed/expected ratio (o/e) 1.04, 90% interval 0.91 to 1.17.
Gene-disease validity (ClinGen):
ClinGen rates the evidence that CALR3 causes each of these diseases.
hypertrophic cardiomyopathy (autosomal dominant): Disputed. A condition in which the myocardium is hypertrophied without an obvious cause.
Homologues: Orthologues: chimpanzee CALR3 (99% identical), macaque CALR3 (95% identical), dog CALR3 (87% identical), pig CALR3 (84% identical), rat Calr3 (84% identical), rabbit CALR3 (83% identical), mouse Calr3 (83% identical), guinea pig CALR3 (76% identical), Caenorhabditis elegans crt-1 (44% identical). Paralogues in human: CALR (49% identical), CANX (32% identical), CLGN (31% identical).
Diseases named in the same sentence as CALR3 in open-access papers:
CALR3 is named in the same sentence as 12 diseases in open-access papers, as found by Europe PMC text mining. Sharing a sentence is not in itself a finding about the gene and the disease. The quoted sentences say what the papers report.
cardiomyopathy (2 papers, 2018 to 2025). A disease of the heart muscle or myocardium proper. "In our national cardiomyopathy cohort (n = 6154), we identified 17 unique, rare heterozygous CALR3 variants in 48 probands." (PMID 29988065, 2018). "In nine probands, the CALR3 variant was accompanied by a disease-causing variant in another, well-known cardiomyopathy gene." (PMID 29988065, 2018). "On the basis of these findings, it seems highly questionable that variants in CALR3 are a monogenic cause of cardiomyopathy." (PMID 29988065, 2018). "In our cohort of 6154 patients with cardiomyopathy, we identified 46 unique heterozygous CALR3 variants." (PMID 29988065, 2018). "For this purpose, we assessed the frequency, distribution and potential effect of CALR3 variants in a Dutch cohort of 6154 cardiomyopathy patients." (PMID 29988065, 2018). "(i) In approximately one-fifth of the probands, the CALR3 variant was accompanied by a disease-causing variant in another, well-known cardiomyopathy gene." (PMID 29988065, 2018). "We investigated the frequency and characteristics of CALR3 variants in a large Dutch cardiomyopathy cohort." (PMID 29988065, 2018). "Based on several observations in this study, we question the impact of CALR3 genetic variation on cardiomyopathy." (PMID 29988065, 2018). "Based on our findings, we highly question the implication of CALR3 in cardiomyopathy." (PMID 29988065, 2018). "In this study, we assessed the role of the calreticulin-3 gene (CALR3) in cardiomyopathy." (PMID 29988065, 2018). "Our data suggest that CALR3 variants are not monogenic causes of cardiomyopathy, if cardiovascular disease-related at all." (PMID 29988065, 2018). "CALR3 has been included in several cardiomyopathy gene panels worldwide." (PMID 29988065, 2018). "However, since the initial report, no other studies have confirmed the association between CALR3 and cardiomyopathy." (PMID 29988065, 2018). "In addition, although our data do not support a role of CALR3 in cardiomyopathy as single-gene disorder, a more complex pattern of inheritance cannot be ruled out." (PMID 29988065, 2018).
breast carcinoma (1 paper, 2015). "Analysis of ADAM2, CALR3 and MAGE-A expression in cohort 2 consisting of 121 breast cancers of different receptor status." (PMID 26252478, 2015). "In this study, we investigated the expression of the cancer/testis antigens ADAM2, CALR3 and SAGE1 in lung and breast cancer, the two most frequent human cancers, with the purpose of providing novel therapeutic targets for these diseases." (PMID 26252478, 2015). "We investigated the potential of three previously uncharacterized CT antigens, ADAM2, CALR3 and SAGE1, as targets for treatment of lung and breast cancer." (PMID 26252478, 2015). "Analysis of ADAM2, CALR3, SAGE1 and MAGE-A expression in cohort 1 consistent of 68 breast cancers of different clinical stages." (PMID 26252478, 2015). "In conclusion, ADAM2, CALR3 and SAGE1 should not be considered targets for treatment of lung and breast cancer." (PMID 26252478, 2015). "Surprisingly, we detected no ADAM2, CALR3 and SAGE1 in the 67 lung cancers (mainly non-small lung cancer) and 189 breast cancers, while MAGE-A proteins were present in 15% and 7–16% of these tumor types, respectively." (PMID 26252478, 2015).
dilated cardiomyopathy (1 paper, 2022). Cardiomyopathy which is characterized by dilation and contractile dysfunction of the left and right ventricles. "Variants of uncertain significance (VUS) were found in 17 cases (eight resuscitated and nine dead) in genes associated with HCM or dilated cardiomyopathy (DCM), such as TTN, TNNT2, MYH6, DSP, ACTN2, CALR3, and MYH7." (PMID 36588553, 2022).
familial hypertrophic cardiomyopathy (1 paper, 2011). Hypertrophic cardiomyopathy caused by mutations in the genes encoding components of the sarcomere, in the absence of predisposing conditions. "These SNPs on chromosome 19p13 associated with lymphocyte counts are proximal to candidate genes such as CHREP, which function in calcium homeostasis in lymphocytes, and mutations in the coding region of CALR3 are associated with familial hypertrophic cardiomyopathy." (PMID 21738480, 2011).
lung carcinoma (1 paper, 2015). "We used a set of previously uncharacterized antibodies against the cancer/testis antigens ADAM2, CALR3 and SAGE1 to investigate their expression in a large panel of normal tissues as well as breast and lung cancers." (PMID 26252478, 2015). "To this end, we have identified antibodies suitable for immunostaining of the three novel CT antigens ADAM2, CALR3 and SAGE1, and characterized the expression of these proteins in normal tissues and the two most common types of human malignancies, breast and lung cancer." (PMID 26252478, 2015). "Our results suggest that ADAM2, CALR3 and SAGE1 cancer/testis antigens are not promising targets for immunotherapy of breast and lung cancer." (PMID 26252478, 2015).
myopia (1 paper, 2023). "Additionally, we identified 4 significant DEGs of myopia: KIAA1211, CALR3, DNASE2B, and CCDC178, and 2 common targets: AR and TYRO3 among DZP, myopia, DEG analysis, and WGCNA." (PMID 37747014, 2023).
Obesity (1 paper, 2024). Accumulation of substantial excess body fat. "CALR3 is responsible for the respective protein that participates in calcium ion binding and may be associated with obesity in chickens." (PMID 38674458, 2024).
tumor (2 papers, 2015 to 2017). "The gene transcription of Calr3, Hspb1, and Tnfaip6, which are related to immunogenicity induction of dead cells, was up-regulated in the R2016 treated tumor cells." (PMID 28282460, 2017).
infection (1 paper, 2016). The state of being infected such as from the introduction of a foreign agent such as serum, vaccine, antigenic substance or organism. "Our results demonstrate that formate dehydrogenase and calreticulin-3 precursor are required for CMV-P1 infection." (PMID 26751216, 2016).
CALR3 also shares sentences with these, for which no sentence is quoted: cancer (1 paper); cardiac disease (1); cardiovascular disease (1).